MYC (MYC proto-oncogene, bHLH transcription factor)
Diseases named in the same sentence as MYC in open-access papers (continued):
Sharing a sentence is not in itself a finding about the gene and the disease.
cancer (continued). "In cancer, cells exposed to genotoxic stressors—including chemotherapy, radiation, or oxidative damage—are more likely to accumulate and retain eccDNAs that harbor amplified oncogenes, drug resistance elements, or stress-response regulators such as HSP90, EGFR, and MYC." (PMID 40521196, 2025). "This supports the possibility that cancers can develop resistance to CXCR2 inhibition via the upregulation of HIF1A or MYC expression and suggest that combining drugs targeting CXCR2 and HIF1A or MYC may increase their therapeutic efficacy." (PMID 40050422, 2025). "Similarly, the expression of FOXM1 and its targets correlates with cancer aneuploidy in time (AADEPT score), while other pro-proliferative transcription factors do not show this association (e.g., MYC)." (PMID 39930267, 2025). "Our analysis revealed MYC and YY1 as key elements of double‐negative feedback loops which interconnect core regulatory circuits associated with normal and cancer attractors, indicating that these TFs can potentially act as master regulators for cancer reversion." (PMID 39840939, 2025). "Thus, targeting metabolic regulators like ABHD5 that converge on oncogenic nodes such as c-MYC may provide a novel therapeutic avenue for prostate and other MYC-driven cancers." (PMID 41349769, 2025). "In this respect, CBL0137, a non-genotoxic anti-cancer small molecule belonging to the curaxins family of drugs may be a particularly attractive drug to improve the treatment of MYC-overexpressing TNBCs." (PMID 39706891, 2025). "AAs metabolism, both EAAs and non-essential amino acids (NEAAs), are regulated by MYC, which also modulates metabolic reprogramming, cancer cell anabolism, metabolic enzymes expression, mitochondrial respiration, glycolysis, and fatty acid and nucleotide synthesis in different types of tumors." (PMID 41008653, 2025). "Clinical data from ongoing trials will further clarify whether CDK9 inhibitors can achieve selective therapeutic efficacy against MYC-dependent cancers without prohibitive toxicity." (PMID 40365020, 2025). "The fact that c-MYC replacement could reverse cell cycle arrest but not death strongly suggests that anti-cancer activity is the product of multiple gain-of-function effects." (PMID 40166243, 2025). "The MYC and HSF1 interaction will be the subject of future investigations, as this interaction is likely to be critical to tumorigenesis and perhaps several other functions known to be driven by MYC and HSF1, such as the cancer stem–like population among others." (PMID 39831777, 2025). "According to the results of the GSEA of cancer hallmarks, the high FAMS group was enriched in epithelial-to-mesenchymal transition (EMT), hypoxia, and TNFA signaling via NF-κB, and the low FAMS group was enriched in the G2M checkpoint, MYC targets V1, and DNA repair." (PMID 41049001, 2025). "Moreover, the findings suggest that MYC is a primary driver of oncogenic pathways in MRT and that MYC inhibitors, when accessible, might be applied to treat SNF5-deleted cancers." (PMID 39471843, 2024). "The UBE2O/AMPKα2/mTORC1 axis favors the transcriptional activity of the oncoprotein MYC, generating a positive feedback loop that promotes cancer cell proliferation and epithelial–mesenchymal transformation (EMT) and endows BC cells with cancer stemness properties." (PMID 39272922, 2024). "However, in cancer cells the tight control of TERT transcription is disrupted by the aberrant expression of TERT promoter activators, primarily MYC, and by nuclear factor kappa B (NF-κB) signaling that is considered the master regulator of TERT activation in cancer cells." (PMID 39595108, 2024). "MYC is one of the most commonly activated oncogenes mediating cancer initiation and progression, and it regulates the expression of two immune checkpoints, CD47 and PD-L1, by directly binding to their promoters, leading to the identification of MYC as a target for immunotherapy resistance." (PMID 39199429, 2024).
cancer (continued). "Moreover, CBLL1 silencing on cancer stem cell tumourspheres induces a significant reduction in tumoursphere size, which is accompanied by the downregulation of the stem cell biomarkers LGR5 and c-MYC at both mRNA and protein levels." (PMID 38339195, 2024). "Based on the known mechanisms of action of BET/EP300 inhibition in other cancers (i.e. MYC pathways inhibition) and that at least part of the UPS showed an enrichment of MYC targets, we hypothesized that targeting BET/EP300 proteins in UPS might be an interesting strategy." (PMID 39681067, 2024). "Moreover, we found that protein synthesis or MYC levels were not consistently affected in cells or tumors supplemented with I3P, indicating that these do not mediate cancer cell growth induced by I3P." (PMID 38769298, 2024). "In RAB27A overexpressing cells, displacement of miR-127-3p via exosome secretion may not inhibit the MAPK pathway to gain cancer metastatic potential by activating transcription factors such as the MYC oncogene." (PMID 38685086, 2024). "Currently, there is no treatment for targeting MYCN or MYC in cancer." (PMID 39101440, 2024). "While these genes may still be effective targets for cancer treatment, they may not necessarily be MYC-SL." (PMID 38302473, 2024). "Interestingly, we observed increased activities of glycolysis, TCA cycles, oxidative phosphorylation, and fructose and mannose metabolism in the PIK3CA-E542K and PIK3CA-E542K/c-MYC groups, suggesting metabolic reprogramming occurred during the PI3KCA-driven cancer progression." (PMID 39336111, 2024). "MYC and RAS interaction may also have an impact on cancer cell migration." (PMID 39164274, 2024). "Considering the interdependency between RAS, cyclin E, and MYC, MYC upregulation, in a feedback manner, may contribute to mitigating RAS- and cyclin E-induced RS, generate genome instability at tolerable levels, and promote cancer development." (PMID 39456601, 2024). "This raises the question of whether absence of co-occurrence between AD and cancer be due to variations in MYC activity." (PMID 39684331, 2024). "This expands our findings in another cancer model, where the more pronounced downregulation of PTEN may result from a combination of genetic alterations and transcriptional repression mediated by the YAP/MYC/EZH2 repressive complex." (PMID 39455556, 2024). "Notably, these studies attempted to recapitulate a cancer like state though over expressing MYC, which does not reflect the physiologically relevant stimulation of MYC." (PMID 38493137, 2024). "Furthermore, functional enrichment analysis revealed that activated pathways were mainly cancer-related in the high-PMRS group, such as E2F_targets, G2M_checkpoint, MYC_targets_V1, MYC_targets_V2, EPITHELIAL_MESENCHYMAL_TRANSITION, MITOTIC spindle, and PI3K_AKT_MTOR_signaling." (PMID 38650895, 2024). "Whether endothelial MYC knockdown in vivo induces senescence, which is related to inflammation and cancer, was not evaluated." (PMID 38510176, 2024). "In addition to activating mTORC1, SLC7A5 can also facilitate MYC and EZH2 signaling in cancer cells, while SLC3A2 has also been confirmed to facilitate uncontrolled proliferation of cancer cell through AKT, MAPK, and cell cycle-related P21/P27 signaling pathways." (PMID 38267663, 2024). "Specifically, the effects of the drug on CLBL-1 were largely attributed to the interference on MYC target genes expression and several signaling pathways (JAK/STAT3, mTORC1, NF-kB) involved in cellular processes such as cell survival and proliferation, which are known to be dysregulated in cancer." (PMID 38791684, 2024). "Moreover, we identified a MYC-degrading molecule, A80.2HCl, that efficiently reduces MYC protein levels and overcomes CDK4/6i resistance, shedding light on strategies for the expanded use of CDK4/6i in cancer treatment." (PMID 38424044, 2024).
cancer (continued). "Furthermore, studies in cancers have also identified MYC inhibition as a radiosensitization or chemosensitization mechanism and it should be explored in MB if MP1-induced MYC inhibition is a promising option to be combined with treatment modalities such as chemotherapy and radiotherapy." (PMID 38200580, 2024). "In fact, studies indicate that HIF stimulates the expression of stem cell markers like OCT4, SOX2, NANOG, MYC, and miR-302 in cancer cells, implying that hypoxic niches may have a significant role in transforming non-cancer stem cells into cancer stem cells." (PMID 39201332, 2024). "The fact that AhR intersects with multiple oncogenic signaling pathways suggests that the activation of AhR may offer therapeutic vulnerability in cancer cells where individual pathway components are not easily targeted or ‘druggable’ (e.g., c-MYC)." (PMID 37106727, 2023). "Currently, there are no drugs clinically available for targeting c-MYC in human cancers." (PMID 36765581, 2023). "However, due to c-MYC’s unique properties with respect to a lack of a defined three-dimensional structure, nuclear localization and absence of a targetable enzymatic pocket, targeting c-MYC for cancer treatment has presented a challenge." (PMID 38078012, 2023). "Remarkably, IGF2BP2 governs glutamine uptake and metabolism by upregulating MYC, glutamic-pyruvic transaminase 2 (GPT2), and solute carrier family 1 member 5 (SLC1A5) in AML, which indicates that IGF2BPs could regulate amino acid metabolism in cancers." (PMID 37554271, 2023). "However, some studies using mouse models showed that solo hepatocytic overexpression of c-MYC in adult mice was not sufficient to initiate or promote cancer after a prolonged latency." (PMID 36746917, 2023). "Therefore, it is not surprising that the MYC signaling pathway is considered a potential therapeutic target for cancer therapy due to its role in tumors." (PMID 36966168, 2023). "Our model in which MYCN selectively activates canonical MYC targets through binding promoters and represses cell lineage specific differentiation genes through binding enhancers more fully rationalizes the different oncogenic cellular effects driven by MYCN in different types of cancer cells." (PMID 37781575, 2023). "Moreover, ssGSEA analysis with transcription factor gene sets in 1019 human cancer cell lines (The Cancer Cell Line Encyclopedia, CCLE dataset) indicates that CRE transcription factor (ATF1 and CREB1) activities are positively correlated with MYC targets, NRF1 targets and stemness scores." (PMID 37463926, 2023). "We found that doubling the sample size led to important cancer pathways being identified more stably and regularly in both the single-platform and cross-platform settings, including pathways related to ERB2, NFKB immune infiltration, and RAF in BRCA, and KRAS, MYC, and PRC2-related pathways in GBM." (PMID 36841852, 2023). "In summary, the combined high‐throughput screens using the MYC‐EBOX‐CRISPR library targeting E‐boxes and the Brunello library for gene knockout is a useful tool for genome‐wide identification of E‐boxes which are important for MYC‐dependent networks in cancer cells." (PMID 37519063, 2023). "However, in cancer cells MYC and HIF1α are not incompatible since many cancer types have both MYC and HIF1α in high levels." (PMID 37601651, 2023). "In particular, CDK9 emerged as a druggable target for the development of cancer therapeutics, due to its crucial role in the transcriptional regulation of both short-lived anti-apoptotic proteins and oncogenes, such as BCL2/6 and MYC, critical for the survival of transformed cells." (PMID 37457123, 2023). "Metabolites can regulate chromatin or protein acetylation (e.g., c-MYC, HIF-1α, GAPDH, PKM2, PEPCK, 6PGD, ACLY, LCAD, and BCAT2), histone succinylation, butyrylation, lactylation, phosphorylation, citrullination, and itaconation, and further contribute to cancer progression." (PMID 36831413, 2023).
cancer (continued). "Therefore, it is not surprising that MYC inhibition represents an attractive strategy against many cancer types MYC dimerizes with MAX through the bHLHZip domain." (PMID 36830948, 2023). "Interestingly, without enhancing cancer development, MYC silencing with shRNA can only suppress USP45-induced stemness and drug resistance." (PMID 36765885, 2023). "CSCs are distinguished from normal cancer cells by activating signaling pathways (including Wnt/beta-catenin, Hedgehog, Notch, TGF-beta and PI3K/AKT/mTOR) and aberrantly expressing transcription factors (including SOX2, Nanog, OCT4 and MYC), which are CSCs’ hallmarks." (PMID 36765885, 2023). "Notably, however, MUC1-C-dependent, MYC-independent signaling was identified for induction of other genes, such as PFKL, ALDOA, and ENO2, that are essential for driving glycolysis and are upregulated in cancer." (PMID 37915591, 2023). "Secondly, this review aims to highlight MYC’s potential as a therapeutic target for innovative cancer treatment approaches by exploring strategies such as inhibiting MYC expression, destabilizing its protein, disrupting MYC/MAX dimerization and combining MYC inhibitors with DNA-damaging agents." (PMID 37755397, 2023). "In the current study, in addition to fundamental expression control of TUG1 by MYC, we found the ATR-CHK1-E2F pathway directly upregulated TUG1 expression in response to HU and CPT exposure (i.e. two hours of treatment), which induced more abundant RS and R-loop, in cancer cells." (PMID 37607907, 2023). "Similarly to cancers within the TCGA cohort, the majority of the basal-like cancers formed a subgroup with a “partial-EMT” gene expression pattern (cluster 3) that was enriched with MYC target genes." (PMID 38111531, 2023). "Therefore, we have hypothesized that via MYC deubiquitination, USP activity can enhance cancer cell stemness and drug resistance." (PMID 36765885, 2023). "However, other functions of MYC that are not directly relevant for cancer biology have not received much attention." (PMID 37495710, 2023). "Interestingly, some in vivo studies demonstrated that hepatocytic overexpression of c-MYC alone in adult mice was not sufficient to initiate cancer or promote cancer after a prolonged latency." (PMID 36746917, 2023). "However, OTUB1 has thus far not been identified as a regulator of c-MYC, a proto-oncogene that is dysregulated in up to 70% of all cancers." (PMID 35159073, 2022). "Thus, the findings indicate that the co-amplification/gain of RIPK2 and MYC, a frequent event in PC and several other cancer types, synergistically contributes to c-Myc protein abundance independent of the cellular context." (PMID 35115556, 2022). "As high c-MYC levels are detected often in TNBC and we recently demonstrated that n-MYC, a closely related paralog of c-MYC, sensitizes cancer cells to NOXA-mediated toxicity, we asked whether c-MYC expression could be a potential factor in TAK-243 efficacy in TNBC." (PMID 36712364, 2022). "However, it turns out that CX-3543 is preferentially concentrated in the nucleoli of cancer cells and inhibits rRNA transcription by RNA Pol I, not at the MYC locus." (PMID 35053227, 2022). "Furthermore, several SE are located near well-known oncogenes, such as MYC, ERG, KIT, BCL2, or TAL1, suggesting that they might also be key players in the pathogenesis of cancers." (PMID 35053311, 2022). "Additionally, oncogenes such as RAS, c-MYC, and HIF-1α are reported to induce glycolysis in cancer." (PMID 36313705, 2022). "Since WNT/Beta-catenin pathway, TGF-beta signaling, c-MYC signaling, and G2/M checkpoint are involved in various aspects of cancer development, downregulation of all these pathways upon exposure to SSRE can be used to predict anti-cancer properties of the extract." (PMID 36079576, 2022).
cancer (continued). "At the same time, there is also evidence that c-MYC levels progressively increase with age, leading to an age-dependent decrease in Nrf2 (nuclear factor erythroid 2 (NFE2)-related factor 2) signaling and adaptive homeostasis, thereby minimizing age-dependent cancer incidence." (PMID 36527013, 2022). "Upon MYC deregulation cells become “egotistic”, so that they do not behave according to environmental cues and improvidently activate proliferative programs, thereby contributing to disease and cancer." (PMID 36430960, 2022). "Furthermore, the mRNA levels of cancer factors including heat shock protein 90 alpha family class B member 1 (HSP90AB1), MYC, and insulin like growth factor 1 receptor (IGF1R) were analyzed by quantitative real-time PCR assay to explore the possible antitumor mechanisms of ME." (PMID 36362498, 2022). "In addition, MYC-driven Group 3 MB are marked by pentose phosphate pathway (PPP) upregulation, which is frequently boosted by cancer cells to provide nucleic acids and nicotinamide-adenine dinucleotide phosphate (NADPH) for cell growth and survival under stressful conditions." (PMID 36340043, 2022). "MYC, CDK2, and cyclin D1 (highlighted by red circles) as part of the CCT2 interactome are shown, supporting that CCT2 could be a central point or node for regulation of cancer proliferation pathways mediated by these factors." (PMID 33996588, 2021). "Knock-down and overexpression studies in cancer cell lines suggest that Usp22 may promote cancer through the positive regulation of well-known oncogenes including BMI1, c-MYC, SIRT1, cyclin B1, and KDM1A, mainly through the regulation of cell cycle progression." (PMID 34503086, 2021). "We cannot rule out the possibility that MYC may also regulate the target genes involved in the pro-cancer function of MYEOV." (PMID 34930894, 2021). "Thus, we hypothesized that, in spontaneously cisplatin-resistant cancer (CDDP-R) cell lines, endogenous PARP1 activity is required for stimulating MYC activities." (PMID 34948122, 2021). "This could have important implications because of the roles of c-MYC in cell metabolism and cancer, revealing new therapeutic opportunities so far not investigated for both ibrutinib and nutlin-3 as alternative molecules to canonical c-MYC inhibitors." (PMID 34287267, 2021). "These molecules have been shown to reduce off‐target effects in biological experiments; ligand 3ao and 3ap could selectively downregulate the expression of c‐MYC and BCL2 genes, respectively via stabilization of promoter quadruplexes and eventually lead to apoptosis in cancer cells." (PMID 34138492, 2021). "Depletion of gRNAs targeting the negative control MYC, a prominent oncogene in a diversity of cancers indicated that proliferation- relevant genes could be identified by the screen." (PMID 33288886, 2021). "Indeed, MYC and UBR5 are often co-amplified in MYC-driven human cancers." (PMID 34178666, 2021).